FOXC1 (forkhead box C1)
Diseases named in the same sentence as FOXC1 in open-access papers (continued):
Sharing a sentence is not in itself a finding about the gene and the disease.
endometrial cancer (19 papers, 2013 to 2025). Primary or metastatic malignant neoplasm involving the endometrium (mucous membrane that lines the endometrial cavity). "In endometrial cancer, miR-204 and miR-495 can suppress the expression of FOXC1 and caused in inhibiting cell growth and migration while increasing apoptosis." (PMID 34493338, 2021). "In endometrial cancer, the downregulation of FOXC1 by miRNA—specifically miRNA 204 and miRNA 495—caused inhibition of cancer cell growth and migration." (PMID 34948036, 2021). "In studies of endometroid endometrial cancer, a pair of tumor suppressor miRNAs—miR-495 and miR-204—are frequently downregulated in association with elevated FOXC1 expression and tumor progression." (PMID 30764547, 2019). "The effect of FOXC1 on the processes of endometrial cancer was validated by FOXC1 gain and loss of function followed by cell viability, colony formation, apoptosis and migration assays." (PMID 26198045, 2016). "In endometrial cancer, decreased expression of miR-204 causes dysfunctional regulation of FOXC1, which results in enhanced metastasis and invasion of tumor cells." (PMID 24321270, 2013). "FOXC1 stimulates VEGF expression via Notch signaling pathways; the association of increased VEGF expression with endometrial cancer angiogenesis shows that FOXC1 is an important angiogenic and prognostic factor." (PMID 40938862, 2025). "The results of our research seem to confirm the significance of FOXC1 in the aggressive phenotype of endometrial cancer cells." (PMID 34948036, 2021). "As in endometrial cancer, this seems to promote progression by amplifying levels of FOXC1 expression." (PMID 30764547, 2019). "Previous studies showed that FOXC1 was directly regulated by antitumor miR-204-5p in laryngeal squamous cell carcinoma and endometrial cancer." (PMID 30866526, 2019). "In endometrial cancer, the downregulation of FOXC1 by miRNA – specifically miRNA 204 and miRNA 495 – was revealed to inhibit cancer cell growth and migration while increasing the frequency of apoptosis." (PMID 29487724, 2018). "HEC1A and Ishikawa endometrial cancer cell lines treated with pre-miR-204 yielded minimized levels of FOXC1 protein and subsequently, reduced cell migration." (PMID 29487724, 2018). "Further research illuminating the pathways in which the miRNAs and FOXC1 interact in endometrial cancer will allow for an understanding of how to halt endometrial cancer progression and suppress endometrial cancer cell migration." (PMID 29487724, 2018). "MicroRNAs – in particular, miRNA 204 (miR204) and miRNA 495 (miR495) – appear to play a part in bridging the observed relationship between FOXC1 and endometrial cancer." (PMID 29487724, 2018). "While MIV generation and IL-8-regulated PI3K/Akt/HIF-α inflammatory signalling pathway are the focus of FOXC1 regulation in HCC, microRNAs take spotlight in FOXC1's relationship with endometrial cancer." (PMID 29487724, 2018). "Dysregulation of microRNA-204 mediates migration and invasion of endometrial cancer by regulating FOXC1." (PMID 28827892, 2017). "Together, these results indicated that miR-495 suppresses the endometrial cancer growth and downregulates the expression of FOXC1 in vivo." (PMID 26198045, 2016). "Here, we found that miR-495 was frequently downregulated, and FOXC1 was overexpressed in endometrial cancer tissues relative to normal tissues." (PMID 26198045, 2016). "In summary, miR-495 functions as a tumour suppressor gene and exhibits its biological role by regulating the expression of FOXC1 in endometrial cancer." (PMID 26198045, 2016). "Knockdown of FOXC1 suppressed, and overexpression of FOXC1 promoted the cell growth and migration of endometrial cancer in vitro." (PMID 26198045, 2016). "Our results reveal the link between miR-495 and the oncogenic factor FOXC1, because FOXC1 was confirmed to be a direct and functional target gene of miR-495 in endometrial cancer." (PMID 26198045, 2016).
endometrial cancer (continued). "Consistently, western blot assay indicated that the expression of FOXC1 in endometrial cancer patients’ tissues was much higher compared with the normal tissues." (PMID 26198045, 2016). "Considering that miR-495 directly regulates the expression of FOXC1 and suppresses cell growth and migration in vitro, we next examined the function of FOXC1 in endometrial cancer." (PMID 26198045, 2016). "Compared with those of the normal tissues, the FOXC1 protein levels were markedly increased in the endometrial cancer patients’ tissues." (PMID 26198045, 2016). "Altogether, these results indicate that miR-495 acts as a tumour suppressor gene by targeting FOXC1 at the post-transcriptional level in endometrial cancer." (PMID 26198045, 2016). "Overall, these results confirmed the relationship between miR-495 and FOXC1 and their functions in endometrial cancer tissues." (PMID 26198045, 2016). "Taken together, our study is the first to document that miR-495 acts as a tumour suppressor gene by negatively regulating FOXC1 in endometrial cancer." (PMID 26198045, 2016). "To further confirm the reduced levels of FOXC1 expression in endometrial cancer tissues, we utilized immunohistochemical staining to detect the FOXC1 protein levels." (PMID 26198045, 2016). "FOXC1 overexpression reversed the cellular responses mediated by miR-495 in endometrial cancer cells." (PMID 26198045, 2016). "In this study, we found that miR-495 reduces cell growth, induces apoptosis and suppresses the migration of endometrial cancer by directly inhibiting FOXC1 expression." (PMID 26198045, 2016). "To identify the target gene responsible for the effects of miR-495 on endometrial cancer, we used bioinformatics and functional knowledge to predict the miR-495 target gene and chose FOXC1 as a candidate." (PMID 26198045, 2016). "A target of miR-204, forkhead box C1 (FOXC1), regulates metastasis and invasion in human endometrial cancer-derived HEC1A cells." (PMID 26535032, 2015). "miR-204 also influences NTRK2 gene expression in neuroblastoma cancer and FOXC1 gene in invasive endometrial cancer." (PMID 26126974, 2015). "miR-204 is reported to act as a tumor suppressor in a variety of cancers through different mechanisms including down-regulation of Bcl-2, NTRK2 in neuroblastoma cancer and suppression of invasion in endometrial cancer mediated by FOXC1 regulation." (PMID 24025188, 2013). "MiR-204 also targets forkhead box C1 (FOXC1), which regulates metastasis and invasion in human endometrial cancer-derived HEC-1A cells." (PMID 24321270, 2013). "In endometrial cancer, the downregulation of FOXC1 by miRNA, specifically miRNA 204 and miRNA 495, inhibits cancer cell proliferation and migration, suggesting that FOXC1 may possibly act as a potential oncogene in endometrial carcinoma." (PMID 40938862, 2025). "The same study identified FOXC1 as a direct target of miR-204 and suggested that they might be involved in progression and metastasis in endometrial cancer." (PMID 29382303, 2018). "Also, miR-204 acts as a tumor suppressor by targeting eighteen genes in head and neck squamous cell carcinoma; miR-204 is deregulated and plays a crucial role in endometrial cancer progression by targeting FOXC1." (PMID 29283424, 2017). "FOXC1 is downregulated by miR-204 and reduces cell migration in endometrial cancer." (PMID 26198045, 2016). "Furthermore, we also performed a transwell migration assay to determine the effect of FOXC1 on cell migration in endometrial cancer." (PMID 26198045, 2016). "Importantly, the overexpression of FOXC1 can reverse the cell functions induced by miR-495 overexpression, indicating that miR-495 reduced the malignancy of endometrial cancer, at least partially, by regulating FOXC1." (PMID 26198045, 2016). "In addition, the inverse correlation between miR-495 and FOXC1 mRNA in endometrial cancer cells and tissues further supported this conclusion." (PMID 26198045, 2016).
endometrial cancer (continued). "Furthermore, real-time PCR was also performed in five endometrial cancer cell lines, and the opposite trend was observed in the miR-495 and FOXC1 mRNA expression, which is consistent with the regulation between them." (PMID 26198045, 2016). "Further exploration into the downstream regulation of FOXC1 by miR204 and miR495 as well as the pathways in which interactions are involved will lead to a greater understanding of how to mitigate more aggressive phenotypes of endometrial cancer with high metastatic potential." (PMID 29487724, 2018). "Additionally, FOXC1 acts as an oncogene in endometrial cancer." (PMID 26198045, 2016). "Using these programs, we selected FOXC1 as a miR-495 target gene for further study due to the malignancy phenotype in other types of cancer, which might be consistent with the phenotype of miR-495 in endometrial cancer." (PMID 26198045, 2016). "The impact of changes in OGT and TET3 amounts on the expression of genes involved in epithelial-mesenchymal transition (FOXA1, FOXC1, TWIST, ZEB1) in endometrial cancer cells has been analyzed." (PMID 34948036, 2021). "Here, we demonstrated that in endometrial cancer cells both TET3 and OGT affected the expression of genes involved in epithelial to mesenchymal transition (EMT), i.e., FOXC1, TWIST1, and ZEB1." (PMID 34948036, 2021). "In conclusion, our results showed that both TET3 and OGT are involved in the regulation of FOXC1, TWIST1, and ZEB1 in endometrial cancer and affect cancer cell migration and invasion." (PMID 34948036, 2021). "Intriguingly, a rescue experiment involving the overexpression of FOXC1 abrogated miR495's inhibition of cell growth and migration as well as promotion of apoptosis in AN3CA and KLE cells (endometrial cancer cells)." (PMID 29487724, 2018). "FOXC1 knockdown by siFOXC1 reduces the migration and invasion of HEC1A cells in endometrial cancer cells." (PMID 26198045, 2016). "FOXC1 is a major member of the FOX protein family, exhibiting abnormal expression in endometrial cancer and potentially influencing the migration and invasion of this malignancy; however, its mechanism of action is unknown." (PMID 40938862, 2025). "Although studies of FOXC1 in endometrial cancer are not advanced, it is suggested that FOXC1 may be a potential oncogene also in endometrial carcinoma." (PMID 34948036, 2021). "The results demonstrated that the expression levels of FOXC1 in the AN3CA/miR-495 and KLE/miR-495 groups were reduced by approximately 70.5 % and 62.50 %, respectively, compared with the negative control, which were consistent with the results from endometrial cancer cells in vitro." (PMID 26198045, 2016).
lung carcinoma (19 papers, 2016 to 2025). "Elevation of tissue DHA in vivo, therefore, would also cause the same changes in miR-138-5p and FOXC1 as those observed in the cultured lung cancer cells." (PMID 31783879, 2019). "In cell invasion assay, although RvD1 treatment led to 42% reduction in lung cancer cell invasion, overexpression of FOXC1 significantly attenuated the effect to a 23% loss of cell invasive ability." (PMID 31783879, 2019). "During the occurrence of lung cancer, abnormally expressed FOXC1 can activate corresponding signaling pathways by promoting lysyl oxygen (LOX) transcription, thereby accelerating tumor metastasis." (PMID 39093497, 2024). "The FOXC1 is a model hypoxia-induced transcription factor that is essential in promoting lung cancer cells' growth, migration, invasion, angiogenesis, and transformation from epithelial to mesenchymal state." (PMID 37925496, 2023). "And miR-138-5p can inhibit the malignant progression of prostate cancer and lung cancer growth, through the miR-138-5p/FOXC1 pathway." (PMID 33299863, 2020). "Specifically, in lung cancer, FOXC1 plays a critical role in tumor microenvironment-promoted cancer progression." (PMID 31783879, 2019). "For instance, FOXC1 mRNA and protein levels are upregulated in 60% and 63.3%, respectively, of patients with non-small cell lung cancer (NSCLC), which is the main type of lung cancer, and FOXC1 knockdown inhibits proliferation and metastasis in NSCLC." (PMID 30189871, 2018). "The changing landscape of tumor biology reveals a growing body of proof indicating that FOXC1 is elevated in multiple types of malignant tumors, such as Lung cancer, triple-negative breast cancer, liver cancer, and gastrointestinal tumors, causing poor prognosis to these patients." (PMID 39093497, 2024). "DHA inhibited proliferation and progression of A549 non-small cell lung cancer cells through ROS-mediated inactivation of the PI3K/Akt pathway, and also through the miR-138-5p/FOXC1 pathway in A549 and H1299 human lung cancer cell lines and LLC murine lung cancer cells." (PMID 32526973, 2020). "Importantly, we found that RvD1 exerted these effects by modulating the miR-138-5p/FOXC1 pathway in lung cancer cells." (PMID 31783879, 2019). "Silencing FOXC1 may significantly inhibit the migration of lung cancer cells by changing the EMT process through inhibiting expression of cadherin, being associated with the expressions of extracellular MMPs." (PMID 29552326, 2018). "In lung cancer, it was demonstrated that HIF-1α binds to the hypoxia-element in the FOXC1 promoter and drives FOXC1 transcription, resulted in enhanced tumor progression." (PMID 33854062, 2021). "The data are clear on elevated FOXC1 expression being a predictor of lung cancer progression, but are not yet available with regard to predicting spread outside of the primary organ." (PMID 34540690, 2021). "For instance, downregulation of EGFR, Forkhead box C1 (FOXC1) and Forkhead box Q1 (FOXQ1) by miR-133 was thought to mediate reduced cell proliferation, migration and invasion of prostate cancer 14, pituitary adenoma 22 and lung cancer 23, respectively." (PMID 34335946, 2021). "In 60 lung cancer cases (30 LUSC and 30 LUAD), in situ hybridization assays were used to detect miR-138-5p expression, and immunohistochemistry assays were used to detect FOXC1 expression." (PMID 31783879, 2019). "We found omentin to be consistently downregulated in lung cancers, and it exhibited a negative correlation with important transcription factors FOXA1, EN1, FOXC1 and ELK4." (PMID 33450975, 2021).
acute myeloid leukemia (15 papers, 2016 to 2025). Acute myeloid leukemia (AML) is a group of neoplasms arising from precursor cells committed to the myeloid cell-line differentiation. "Moreover, in cases of acute myelogenous leukaemia, FOXC1 knockdown induces the loss of repressor proteins, the gain of CCAAT Enhancer Binding Protein Alpha (CEBPA) binding and the upregulation of nearby genes." (PMID 38429902, 2024). "We recently reported that the Forkhead box transcription factor FOXC1 is misexpressed in approximately 20% of patients with acute myeloid leukemia (AML), in particular in those cases exhibiting high HOXA/B gene expression." (PMID 29346763, 2018). "Additionally, in acute myeloid leukemia (AML), WBP5 overexpression has been associated with poor prognosis, correlating with increased expression of HOX gene cluster (HOXA5, HOXA7, HOXA9, and HOXA10), MEIS1, and FOXC1." (PMID 40002180, 2025). "In patients with acute myeloid leukemia (AML), ectopic expression of FOXC1 significantly inhibits KLF4 expression." (PMID 35504885, 2022). "Despite absent expression in normal hematopoiesis, the Forkhead factor FOXC1, a critical mesenchymal differentiation regulator, is highly expressed in ∼30% of HOXAhigh acute myeloid leukemia (AML) cases to confer blocked monocyte/macrophage differentiation." (PMID 34551306, 2021). "Overexpression of the family member FOXC1 has been reported in solid tumors and acute myeloid leukemia (AML)." (PMID 29137406, 2017). "FOXC1 was expressed in more than 20% of human Acute Myeloid Leukemia (AML) patients while there was no expression of FOXC1 in normal hematopoietic populations." (PMID 29552326, 2018). "Additionally, FOXC1, typically absent in normal hematopoiesis, is highly expressed in certain acute myeloid leukemia (AML) subtypes." (PMID 40032852, 2025).
COVID-19 (15 papers, 2022 to 2024). A disease caused by infection with severe acute respiratory syndrome coronavirus 2. "The identified TFs, such as FOXC1, GATA2, YY1, FOXL1, FOXO3, STAT1 and STAT3, are associated with COVID-19." (PMID 37261353, 2023). "A recent study about the genomics of COVID-19 showed that TFs like FOXC1, GATA2, YY1, FOXL1, and NFKB1 regulated the inflammatory network in SARS-CoV-2 infections." (PMID 35747501, 2022). "We suggest that FOXC1 and hsa-mir-4459 have potential as key biomarkers or therapeutic targets for treatment of T1DM after COVID-19 convalescence." (PMID 38169604, 2023). "Based on previous studies, most of these 11 TF, especially FOXC1 and STAT3 are involved in the progression of COVID-19 and heart-related diseases." (PMID 36420258, 2022). "In our analysis, FOXC1, GATA2, YY1, and PPARG may play a role in the development of COVID-19 and IS." (PMID 37184686, 2023). "FOXC1, YY1, GATA2, FOXL, STAT1 and STAT3 are important TFs for COVID-19." (PMID 37261353, 2023). "Forkhead-box C1 (FOXC1) is a TF that regulates the expression of CD3G and YES1, and may therefore affect the development of T1DM after COVID-19 convalescence." (PMID 38169604, 2023). "Furthermore, our research indicates that transcription factors FOXC1, GATA2, YY1, NR2C2, and E2F4 were overexpressed in common DEGs of psychiatric disorders and COVID-19." (PMID 35185890, 2022).
non-small cell lung carcinoma (15 papers, 2016 to 2024). A group of at least three distinct histological types of lung cancer, including non-small cell squamous cell carcinoma, adenocarcinoma, and large cell carcinoma. "FOXC1 promotes the development of cancer stem-like characteristics in non-small cell lung cancer by upregulating ꞵ-catenin expression." (PMID 39596660, 2024). "FOXC1 is upregulated in non-small-cell lung cancer tissues and is negatively correlated with patient survival." (PMID 34957298, 2021). "As another example, FOXC1-mediated LINC00301 triggers malignant potential of non-small cell lung cancer cells and modulates the Tregs and CD8+ T cell populations by activating TGF-β signaling (Sun C.-C." (PMID 33665192, 2021). "This study investigates the regulatory effects of FOXC1 on CSC-like properties in non-small cell lung cancer (NSCLC)." (PMID 30189871, 2018). "FOXC1 is also involved in the cell cycle, as the high expression of FOXC1 in non-small-cell lung carcinoma has been shown to induce CCND1 expression, which is responsible for accelerated G1–S phase transition." (PMID 28577032, 2017). "Furthermore, a FOXC1 and miR-335-5p network was presented in non-small-cell lung cancer, type 2 diabetes, and vascular dementia." (PMID 37082197, 2023). "In addition, FOXC1 is overexpressed in non-small cell lung cancer (NSCLC) cells and is negatively correlated with the survival of the patients." (PMID 30360388, 2018). "FOXC1 mediates LINC00301 to promote the tumor progression and generate an immunosuppressive microenvironment in non-small cell lung cancer." (PMID 38111678, 2023). "In non-small cell lung cancer (NSCLC) cells, knockdown of FOXC1 impaired self-renewal, downregulated CD133 and other ‘stemness’ markers, dampened in vivo tumorigenicity, and increased sensitization to chemotherapy." (PMID 30764547, 2019). "FOXC1 mediates the high expression of an oncogenesis long intergenic non-coding RNA 00301, which increases regulatory T cell (Treg) infiltration while decreasing CD8+ T cell infiltration in non-small cell lung cancers." (PMID 36622275, 2023).